CENPC (centromere protein C)
Description:
Component of the CENPA-NAC (nucleosome-associated) complex, a complex that plays a central role in assembly of kinetochore proteins, mitotic progression and chromosome segregation. The CENPA-NAC complex recruits the CENPA-CAD (nucleosome distal) complex and may be involved in incorporation of newly synthesized CENPA into centromeres. CENPC recruits DNA methylation and DNMT3B to both centromeric and pericentromeric satellite repeats and regulates the histone code in these regions.
Synonyms: CENP-C; CENPC1; hcp-4; MIF2
Tractability: PROTAC: UniProt records ubiquitination sites on it; ubiquitination databases record sites on it; its protein half-life has been measured.
Gene: Protein-coding gene on chromosome 4 (67,468,762 to 67,545,563, reverse strand). Ensembl gene ENSG00000145241.
Subcellular location: Nucleus; Chromosome, centromere, kinetochore; Chromosome, centromere
Subcellular location (Human Protein Atlas): Kinetochore; Nuclear bodies; Midbody; Nucleoplasm
Pathways (Reactome):
Cell Cycle: Amplification of signal from unattached kinetochores via a MAD2 inhibitory signal; Deposition of new CENPA-containing nucleosomes at the centromere; EML4 and NUDC in mitotic spindle formation; Mitotic Prometaphase; Resolution of Sister Chromatid Cohesion; Separation of Sister Chromatids
Signal Transduction: RHO GTPases Activate Formins
Gene Ontology:
Molecular function: identical protein binding; protein binding; centromeric DNA binding; DNA binding
Biological process: chromosome segregation; kinetochore assembly; mitotic cell cycle; attachment of mitotic spindle microtubules to kinetochore; spindle attachment to meiosis I kinetochore; chromosome organization
Cellular component: condensed chromosome, centromeric region; inner kinetochore; kinetochore; nuclear body; nucleoplasm; nucleus; pericentric heterochromatin; cytosol; chromosome, centromeric region
Genetic constraint (gnomAD): Loss-of-function variants: 23 observed, 36.79 expected, observed/expected ratio (o/e) 0.63, 90% interval 0.45 to 0.89. The upper end of that interval is the gene's LOEUF score, 0.89, which puts it in group 3 of 6, group 1 being the genes least tolerant of losing a copy. Missense variants: 512 observed, 543.19 expected, observed/expected ratio (o/e) 0.94, 90% interval 0.88 to 1.01. Synonymous variants: 176 observed, 184.83 expected, observed/expected ratio (o/e) 0.95, 90% interval 0.84 to 1.08.
Homologues: Orthologues: chimpanzee CENPC (99% identical), macaque CENPC (88% identical), rabbit CENPC (69% identical), pig CENPC (68% identical), guinea pig CENPC (62% identical), dog CENPC (59% identical), rat Cenpc (53% identical), mouse Cenpc1 (50% identical), tropical clawed frog cenpc (24% identical), zebrafish si:ch211-161h7.4 (14% identical).
Diseases named in the same sentence as CENPC in open-access papers:
CENPC is named in the same sentence as 18 diseases in open-access papers, as found by Europe PMC text mining. Sharing a sentence is not in itself a finding about the gene and the disease. The quoted sentences say what the papers report.
colorectal cancer (3 papers, 2015 to 2025). A primary or metastatic malignant neoplasm that affects the colon or rectum. "We used 9 different spatial distribution models to mimic the centromeric localization observed in HCT116-Cas9 colorectal cancer cells stained for the CENP-centromere protein CENP-C, which stably binds to centromeres throughout the cell cycle." (PMID 40214445, 2025). "We used 9 different spatial distribution models to mimic the centromeric localization observed in HCT116-Cas9 colorectal cancer cells stained for the CENP-Centromere protein CENP-C, which stably binds to centromeres in interphase nuclei." (PMID 39896519, 2025).
osteoarthritis (1 paper, 2013). A noninflammatory degenerative joint disease occurring chiefly in older persons, characterized by degeneration of the articular cartilage, hypertrophy of bone at the margins and changes in the synovial membrane. "In particular, centromere protein-C, insulin growth factor binding protein 2, and LDH have not been previously linked to an imbalance of damage and repair in osteoarthritis, whereas, TNC and COL2A1 have already been reported." (PMID 23773399, 2013).
sarcopenia (1 paper, 2021). Progressive decline in muscle mass due to aging which results in decreased functional capacity of muscles. "For instance, the CENPC expression was elevated in the sarcopenia of SSS and HSS, but not in that of JSS." (PMID 34704369, 2021).
viral infection (1 paper, 2017). "Similar to how centromeres can have cell cycle-specific interactions with the nuclear envelope, it has also been suggested that they can have cell cycle-specific interactions with PML/ND10 bodies, at least in the case of CenpC during viral infection." (PMID 28346356, 2017).
CENPC also shares sentences with these, for which no sentence is quoted: cancer (8 papers); tumor (6); systemic sclerosis (5); calcinosis (2); CREST syndrome (2); Telangiectasia (2); autoimmune disease (1); Autoimmunity (1); colorectal adenocarcinoma (1); colorectal tumors (1); esophageal (1); infection (1); metastatic prostate carcinoma (1); schizophrenia (1).